HGF (hepatocyte growth factor)
Diseases named in the same sentence as HGF in open-access papers (continued):
Sharing a sentence is not in itself a finding about the gene and the disease.
tumor (continued). "Besides VEGF, neutrophils are known to secrete other tumor-promoting factors, including hepatocyte growth factor, interleukin-8 (IL-8), IL-6, and tumor necrosis factor, creating a favorable microenvironment for tumor survival." (PMID 33897913, 2021). "Complemented by ex vivo tumor organoid experiments, this study show that Lgr5− colorectal cancer cells have a basal ability to give rise to Lgr5+ cells, and that this process can be boosted by supportive-niche factors like HGF and FGF." (PMID 33671641, 2021). "Some tumor cell associated cytokines such as cytokines and angiogenic factors (CAFs)which can support the proliferation of tumor cell.FGF-2, HGF, VEGF, and PDGF-β plasma levels at diagnosis are indicative of more profound response since lower angiogenesis to MM cell." (PMID 34290698, 2021). "By expressing HGF, PSCs act in a paracrine way on the tumor cells expressing MET." (PMID 34298732, 2021). "Here, we show that IL-6 and HGF, secreted by tumor neighboring visceral adipose stromal cells (V-ASCs), expand the metastatic colorectal (CR) cancer cell compartment (CD44v6 + ), which in turn secretes neurotrophins such as NGF and NT-3, and recruits adipose stem cells within tumor mass." (PMID 34408135, 2021). "There was increased c-MET expression observed in both inflammatory and tumor-induced lymphatic vessels, and HGF-c-MET interaction could indirectly upregulate the VEGF/VEGFR expression via activating NF-kB molecule." (PMID 35087755, 2021). "In addition, it was demonstrated that CAF promoted the tumour‐initiating cell plasticity of HCC through the activation of HGF/c‐Met cascade thus enhanced HCC tolerance to chemotherapeutic agents." (PMID 33713546, 2021). "This panel was also determined its function in tumor progression via the HGF/c‐Met axis." (PMID 33751856, 2021). "In colon cancer, increased Rab31 expression may promote tumor progression by regulating HGF secretion in the tumor stroma." (PMID 34141705, 2021). "Thus, a combination treatment of HGF and free anti-PD-L1 antibody was conducted to explore their anti-tumor synergy." (PMID 34593794, 2021). "Pseudopalisades secrete hypoxia-inducible factor (HIF-1), vascular endothelial growth factor (VEGF), hepatocyte growth factor (HGF), matrix metalloproteases (MMPs), and interleukin-8 (IL-8) that promote microvascular proliferation, angiogenesis, and tumor expansion." (PMID 33670551, 2021). "It has been found that the HGF/c-Met signaling pathway may influence multiple aspects of tumor development by activating specific pathways that induce interactions between cancer cells and the tumor microenvironment in which they reside." (PMID 34745947, 2021). "The tumor weight of HGF-treated PDX tumors was significantly higher than untreated PDX tumors." (PMID 34439392, 2021). "Increased ROS levels in stromal fibroblasts by transforming growth factor beta-1 (TGFß1) initiated the mesenchymal–mesenchymal transition (MMT) and secretion of vascular endothelial growth factor (VEGF), hepatocyte growth factor (HGF), and interleukin-6 which are biomarkers for invasive tumor cells." (PMID 33435480, 2021). "LEF-1 cross-talks between HGF/c-Met and Wnt/β-catenin to coordinate tumor migration and invasion." (PMID 34737955, 2021). "Hepatocyte growth factor (HGF) is a cytokine produced by many interstitial cells, such as fibroblasts and macrophages, and acts on the receptor tyrosine-protein kinase Met (c-Met) on the surface of tumor cells." (PMID 34970492, 2021). "Next, B16F10 tumor-bearing mice were used to determine the exosome inhibition of HGF NPs in vivo." (PMID 34593794, 2021). "Additionally, in U87 MG tumor-bearing nude mice, HGF Nbs inhibited tumor growth, and cures were observed in 50–67% of mice, indicating therapeutic potential." (PMID 34575943, 2021). "Upon binding to its receptor MET, HGF can promote the invasion and metastasis of tumor cells." (PMID 33732214, 2021).
tumor (continued). "On the other hand, myCAF-secreted hyaluronan and iCAF-secreted HGF exerted tumor-promoting effects." (PMID 34681633, 2021). "Based on our in vitro results, we hypothesized that targeting HGF could modulate Treg in tumor-bearing patients." (PMID 34771724, 2021). "HGF/MET-induced neutrophils activation produces nitric oxide that kills tumor cells directly." (PMID 34771620, 2021). "To mimic physiological conditions, we stimulated tumor cells with HGF." (PMID 34127734, 2021). "Furthermore, we found that curcumin inhibited tumor growth and HGF-induced EMT in mice subjected to subcutaneous xenotransplantation." (PMID 34408780, 2021). "A previous study found that HGF is commonly secreted by stromal cells and then activates the Met receptors in tumor cells by paracrine in the tumor microenvironment, while HGF autocrine by tumor cells rarely occurs." (PMID 34970484, 2021). "Previous studies showed that HGF plays a role in promoting tumor angiogenesis." (PMID 33718248, 2021). "Moreover, these CAFs showed enhanced secretion of hepatocyte growth factor (HGF), which promoted tumor growth through HGF–Met signaling." (PMID 33614646, 2021). "Notably, HGF NPs treatment induced the highest increase in tumor-infiltrating cytotoxic and helper T lymphocytes (CD3+CD8+ and CD3+CD4+) due to the combination of relieved immunosuppression of exosomal PD-L1 and enhanced ferroptosis." (PMID 34593794, 2021). "FAK may be involved in HGF-induced cell motility, and that renders MET-expressed tumor cells susceptible to transformation by HGF stimulation to promote migration and invasion." (PMID 34771620, 2021). "NRP1 could promote tumor progression through potentiating the activity of the HGF/SF autocrine c-Met signaling pathway." (PMID 33995640, 2021). "Interestingly, MET induces MAPK re-activation in all tested HNSCC models, and blocking of MAPK with a MET inhibitor re-sensitized the HGF-stimulated tumor cells to cetuximab." (PMID 33596979, 2021). "Hepatocyte growth factor (HGF) can promote the growth of tumor cells and blood vessels." (PMID 35111071, 2021). "HGF/c-Met signaling plays an important role in promoting tumor angiogenesis, growth and metastasis." (PMID 34050266, 2021). "Hepatocyte growth factor (HGF) is a stroma-derived marker of the tumor microenvironment that may affect tumor progression differentially by race." (PMID 34344422, 2021). "The pharmacological inhibition of PRMT5 by 5′-methylthioadenisine (MTA) or the inhibition of PRMT5 using ShRNA increased RAS-ERK1/2 activity in response to hepatocyte growth factor (HGF) and resulted in tumor suppressive effects by downregulating EGFR and RAF1 signaling in PC12 tumor cells." (PMID 33670008, 2021). "In addition, perioperative pRBC transfusion stimulates tumor growth, the invasion of tumor cells and malignant transformation by increasing the IL-6, vascular endothelial growth factor and hepatocyte growth factor." (PMID 34771598, 2021). "Additionally, a remarkable change in the secreted protein levels of VEGF, bFGF, and HGF in the co-cultured microenvironment was observed, which plays an important role in mediating the tumor-promoting effect." (PMID 34362454, 2021). "Interestingly, CCL7, CCL19, CXCL7, NRG3, SLPI, OPN, and HGF in macrophages are upregulated in response to increased tumor CCL5 expression." (PMID 34298673, 2021). "Furthermore, in vivo tumor accumulation of HGF NPs was evaluated in C57BL/6 J female mice bearing subcutaneous B16F10 tumor model." (PMID 34593794, 2021). "Individual HGF inhibits tumor growth and stimulates long-lasting immunological memory successfully." (PMID 34593794, 2021). "Our results give additional support for testing whether this approach could be beneficial in patient subgroups with tumours overexpressing the HGF/Met axis." (PMID 32946618, 2020).
tumor (continued). "Further investigation in oncological models will address whether HGF-Timp1-based preventive cardioprotective therapy could lead to a tumor-protecting effect in the context of anthracycline chemotherapy." (PMID 32722178, 2020). "The positive correlation of tumor purity and c-Met expression demonstrated the tumoral expression of c-Met unlike a microenvironmental expression of HGF that has a negative association with tumor purity (cor = 0.041, P = 4.24e-01)." (PMID 32788873, 2020). "HGF/MET signaling can stimulate various downstream signaling pathways in tumor cells, such as PI3K/AKT, JAK/STAT, Ras/MAPK, SRC, and Wnt/β-catenin, and it can enhance tumor malignancy by inducing biological processes such as tumor proliferation, invasion, and metastasis." (PMID 33066121, 2020). "In order to ascertain whether the abrogation of fibroblast-secreted HGF by curcumin was responsible for decreased invasive capacity of tumour cells in the co-culture model, we used lentiviral transduction to create a stable MRC5 HGF knockdown." (PMID 31963196, 2020). "In addition, hepatocyte growth factor (HGF) increases PD-L1 concentration in different tumor cell lines." (PMID 33233528, 2020). "Moreover, the HGF/c-Met axis is regarded as a tumor aggressiveness and prognosis biomarker of patients with HCC." (PMID 32117981, 2020). "In ES cells, HGF treatment significantly increased the tumor mass and metastasis." (PMID 32754598, 2020). "Thus inhibition of HGF can exert anti-tumor effect with maintaining cell-to-cell junctions via stabilizing desmosomes by DSG1 overexpression." (PMID 32564264, 2020). "With regard to fibrosis, collagen deposition was largely unaffected by the treatments, except interestingly, the HGF-neutralising antibody + c-MET inhibitor (Hi + Ci)-treated tumours, which showed a significant decrease in collagen content when compared with those treated with gemcitabine alone." (PMID 32203220, 2020). "That is to say, heterogeneous HCC populations might respond in disparity on HGF-stimulated tumor growth and metastasis." (PMID 32206115, 2020). "They first verified the overexpression of lncRNA UCA1 in MM and clarified its tumor-promoting effect (mainly facilitating proliferation and reducing apoptosis) could be regulated by miR-1271-5p/HGF axis." (PMID 32083078, 2020). "Furthermore, molecular changes leading to tumor heterogeneity are also regulated by local microenvironment cues (e.g., interactions with non-tumor cells, hypoxia, stroma-derived factors HGF, TGF-β)." (PMID 33202944, 2020). "Our studies demonstrated that SDF-1 and HGF, which may stimulate tumor cells to form metastases, increase the SNAIL level by inducing GSK3β phosphorylation via the PI3K-AKT pathway." (PMID 32664538, 2020). "Simultaneous targeting of both tumor angiogenesis and the HGF-mediated invasion and metastasis could form a new approach to treating patients with PDA peritoneal metastasis." (PMID 32780245, 2020). "Thirdly, the growth factors EGF and HGF in the gastrocnemius have the same correlation profile: positive between them and with the activation of the NFκB inflammation pathway in inguinal adipose tissue, and also with the amount of tumour EGF." (PMID 32472095, 2020). "Importantly, our data also demonstrated that the expression of c-Met and HGF was reduced in MACC1-depleted tumor tissues, further confirming our previous findings." (PMID 33425885, 2020). "Support for this notion came from the observation that the MEK inhibitor U0126 attenuates hepatocyte growth factor-induced proliferation in human granulosa-like tumor cell line (KGN cells) and insulin-like growth factor 1-induced, AKT-mediated proliferation in human luteinized granulosa cells." (PMID 31915051, 2020). "By stimulating cell proliferation and angiogenesis, HGF promotes tumor metastasis." (PMID 32607415, 2020).
tumor (continued). "Low levels of HGF and pMet in the tumour cell cytoplasm and high levels of pAkt in the tumour cell nucleus are associated with a larger benefit from RT, indicating that these proteins may be used as biomarkers or treatment targets." (PMID 32946618, 2020). "Collectively, the results of these studies show that HGF/c-Met axis is an effective multifaceted tumor regulator, which could have pivotal implications on the understanding of HCC mechanisms and the improvement of therapeutics." (PMID 32083078, 2020). "The major concern regarding the activation of HGF/MET pathway for therapeutic purposes in vivo is the mitogenic effects that might lead to increased tumor growth." (PMID 32372975, 2020). "HGF released by fibroblast exerts its tumorigenic function by activating the tyrosine receptor, c-Met, on tumor cells, which in turn activates various growth factors and signaling pathways involved in cancer cell proliferation, apoptosis resistance, invasion, angiogenesis and drug resistance 88-90." (PMID 32724474, 2020). "However, significantly decreased cancer cell numbers (due to decreased proliferation as well as increased apoptosis) were observed in tumours treated with gemcitabine alone or in dual or triple combinations with HGF/c-MET inhibitors." (PMID 32203220, 2020). "HGF signaling plays an important role in tumor growth by activating mitogenic signaling pathways." (PMID 32780245, 2020). "The possible pro-tumor effects of these HGF secreting neutrophils was also investigated." (PMID 32117721, 2020). "Interestingly, GGC suppressed tumor cell invasion and migration whereas, HGF treatment mitigated GGC-induced invasion and migration." (PMID 33167504, 2020). "On the contrary, TNF-α induced Met expression in neutrophils, which could release nitric oxide upon HGF stimulation, thereby killing tumor cells." (PMID 32422991, 2020). "HGF/cMET complex plays an important role in tumor progression." (PMID 32766254, 2020). "Secondly, MVs are able to enhance angiogenesis: They stimulate the expression of pro-angiogenic molecules [including matrix metalloproteinase (MMP)-9, VEGF, IL-8 and hepatocyte growth factor (HGF)] in tumor cells and drive capillary tube formation by stimulating endothelial cells." (PMID 31991775, 2020). "The HGF/c-Met signaling pathway has close correlation with tumor growth, invasion and metastasis." (PMID 33374386, 2020). "Likewise, RT to the stroma can increase tumor invasiveness due to increased hepatocyte growth factor (HGF)/c-Met (HGF receptor) signaling and MAPK activity, which enhances tumor mobility and can be deleterious." (PMID 33050580, 2020). "In the brain, for both developing and tumor cells, HGF/MET is highly expressed and functional." (PMID 33066121, 2020). "Additionally, the coordination of tumor metabolism and autophagy are critical for the resistance to HGF/MET-targeted therapy." (PMID 32435640, 2020). "Until routinely applied anticancer drug combinations are available simultaneously targeting HGF, EGF and NFE2L2 mediated pathways, inhibition of overexpressed DYNLL, TNC, NCL and TMED2 may exert anti-tumor effect on HNSCC beyond their diagnostic role." (PMID 32564264, 2020). "In addition, studies have demonstrated that M2, but not M1, macrophages maintain tumor growth and metastasis by secreting hepatocyte growth factor (HGF), thereby significantly increasing tumor resistance to sorafenib." (PMID 32532960, 2020). "IL-6 alone or together with HGF significantly enhanced tumor invasiveness." (PMID 32792856, 2020). "Additionally, the ligand HGF was found to be overexpressed in almost 50% of human tumor tissue samples." (PMID 31940827, 2020). "It is worth noting that TPL2 deficiency on its own is not sufficient to induce tumorigenesis, and TPL2-/- mice tumor susceptibility is dependent on tissue damage, inflammation, NF-κB activation and HGF/c-Met signaling." (PMID 32724474, 2020).
tumor (continued). "As such, we believe that this study provides valuable information of radioresistance mediated by HGF, pMet and pAkt in patient tumour samples, but clearly, further studies are needed to determine how this could be implemented in clinical practice." (PMID 32946618, 2020). "This assumption may be supported by the observations that HCC cell-derived GM–CSF-activated TANs to produce HGF and that the treatment with anti-neutrophil or anti-HGF antibodies reduced tumor formation." (PMID 32422991, 2020). "Neutralization of HGF inhibited cancer cell invasion induced by stromal fibroblasts, suggesting a crucial role of HGF/Met signaling in the interaction between fibroblasts and tumor cells." (PMID 31101063, 2019). "Accordingly, an increased production of tumor lactate and stromal HGF were detected in advanced NSCLC patients upon the emergence of resistance to EGFR TKIs currently used in clinical practice (erlotinib and gefitinib), thus corroborating the clinical relevance of the reported findings." (PMID 30927908, 2019). "This begs the question- what is the concentration of HGF within the tumor microenvironment?" (PMID 30719213, 2019). "Because HGF may increase EGFR-TKI resistance, PD-L1 expression, and immune escape in NSCLC, we explored the regulatory mechanisms of PD-L1 expression in HGF-mediated EGFR-TKI resistant NSCLC tumours." (PMID 31747941, 2019). "The aim of this study was to address whether the increased tumor burden in Tpl2−/− mice is due to aberrant HGF/MET signaling." (PMID 30631034, 2019). "Moreover, compared with immunohistochemistry (IHC) detection of HGF expression in primary NSCLC tissues, the methylation-specific PCR (MSP) detection of HGF promoter methylation levels significantly correlated with advanced tumor stage and metastasis." (PMID 31602259, 2019). "HGF is another cytokine that is involved in EMT induction in tumor cells." (PMID 31096701, 2019). "To note, the level of HGF also decreased significantly in the tumor of PH treated group." (PMID 31372176, 2019). "Il-6 levels did increase over time in some patients with lower baseline levels of IL-6 but these changes occurred gradually and similar to the observed gradual increase in VEGF or HGF levels likely reflecting corresponding increases in tumor burden/progression." (PMID 31426803, 2019). "Fibroblast-restricted deletion of Ikkβ stimulated intestinal epithelial cell proliferation, suppressed tumor cell death, and induced angiogenesis, ultimately resulting in accelerated tumor growth, through a mechanism mediated by the hepatocyte growth factor (HGF)." (PMID 31052449, 2019). "Additionally, this assay has the potential to be optimized with other tumor promoters such as hepatocyte growth factor, epidermal growth factor, and phorbol esters, as well as with complete carcinogens such as BaP." (PMID 31311976, 2019). "We showed that BsAb-5 could inhibit HGF-mediated tumor development, serving as an inhibitory c-MET antibody." (PMID 29187584, 2019). "Moreover, a significant decrease in tumor growth was observed on H69M (mesenchymal cells derived from H69 after HGF exposure) xenografted mice after treatment with PF-2341066 combined with etoposide." (PMID 31547040, 2019). "We showed that BsAb-5 could inhibit hepatocyte growth factor (HGF) mediated tumor development, including proliferation, migration, and apoptosis, serving as an inhibitory c-MET antibody." (PMID 29187584, 2019). "However, when the tumor lines were tested at HGF levels typically detected in human serum (0.4 to 0.8 ng/mL), inhibitor activity was lost." (PMID 30719213, 2019). "This could be one reason for the observed higher chemoresistance in 3D than in 2D as the activation of the HGF signaling pathway protects tumor cells from apoptosis, which is also reported in gefitinib-resistant cell lines." (PMID 31861874, 2019). "This enables the hepatocyte growth factor (HGF), also driven by the tumor, to bind to MET." (PMID 31474975, 2019).